TLR3 (toll like receptor 3)
Diseases named in the same sentence as TLR3 in open-access papers (continued):
Sharing a sentence is not in itself a finding about the gene and the disease.
lung carcinoma (continued). "In cancer cells only, TLR3 acquires additional death receptor properties, which has been reported for an increasing range of different cancers, such as neuroblastoma (NB), hepatocarcinoma, lung cancer or mesothelioma." (PMID 34011952, 2021). "Indeed, we recently demonstrated that aerosol administration of TLR3 agonist poly(I:C) in mouse models impaired lung metastatization through activation of TLRs on lung cancer infiltrating immune cells." (PMID 32093313, 2020). "To determine the relevance of TLR3-induced apoptosis in lung cancer cells in driving good prognosis in NSCLC patients, we explored the expression of cleaved caspase-3 in NSCLC specimens, highlighting that TLR3 expression correlates with cleaved caspase-3 expression in lung adenocarcinoma." (PMID 32093313, 2020). "We examined whether induction of apoptosis in vitro observed upon activation of TLR3 in lung cancer cells also occurs in NSCLC patients with TLR3 expressing tumor." (PMID 32093313, 2020). "Furthermore, a recent report has shown that autophagy functions to TLR4- and TLR3-triggered progression of lung cancer cells through enhancing TRAF6 ubiquitination, indicating the pivotal role of autophagy in cancer progression." (PMID 31620128, 2019). "HIV-infected T-cell exosomes quickly enter recipient cells via epidermal growth factor receptor (EGFR) and subsequently stimulate ERK1/2 (extracellular signal-regulated kinase 1 and 2) phosphorylation in HNSCC and lung cancer cells in an EGFR/Toll-like receptor 3 (TLR3)-dependent manner." (PMID 30389917, 2018). "Hence, polyI:C treatment seemed to have an inverse impact on the viability of lung cancer cells depending on the TLR3 protein level." (PMID 28427199, 2017). "It is conceivable that as long as a cancer cell (e.g. A549, NCI-H292, and NCI-H358) expresses a low-to-medium level of functional TLR3 protein, it will engage polyI:C and becomes responsive to polyI:C treatment, which activates the TLR3 signalling to subsequently kill the lung carcinoma." (PMID 28427199, 2017). "In mice models of breast and lung cancers, TLR3 activation was reported to: (a) elicit chemoattraction of cytotoxic lymphocytes to the growing tumor, (b) induce secretion of type I interferon (IFN) and inflammatory cytokine/chemokine and (c) enhance anti-tumor immune responsiveness." (PMID 28427199, 2017). "Thus, we propose that the expression of TLR3 and secretion of pro-/anti-inflammatory cytokines would correlate with the efficacy of polyI:C (and possibly, Hiltonol) treatment of lung cancer cells." (PMID 28427199, 2017). "Moreover, it was reported that IFN-α up-regulates the expression of TLR3 in lung carcinoma A549 cells and human umbilical vein endothelial cells." (PMID 24155891, 2013). "Next, we examined whether ARRB2 was involved in lung cancer progression induced by TLR3 and TLR4." (PMID 37443143, 2023). "Furthermore, if confirmed in further in-deep study, TLR3 could be considered as a promising lung cancer biomarker for tumor aggressiveness and prognosis." (PMID 34094905, 2021). "In agreement with this hypothesis, in this study we observed that specific stimulation of TLR3 with synthetic TLR3 agonists and INFα is able to induce cell apoptotic program, culminating in the activation of caspase-3 in two human lung cancer cell lines expressing TLR3." (PMID 32093313, 2020). "Additionally, activation of TLR4 and TLR3 stimulated autophagy induction in lung cancer cells and induced enhancements of cytokine productions, such as IL-6, CCL2/MCP-1, CCL20/MIP-3α, VEGFA, and MMP2, by encouraging TRAF6 ubiquitination, thereby led to increases of cell migration and invasion." (PMID 31620128, 2019). "Activation of TLR3 by dsRNA recruits caspase 8 to form a death-signalling complex in the presence of RIP1, which appears not to be stringently dependent on Fas-associated with death domain (FADD) and results in initiation of the extrinsic apoptosis pathway in lung cancer cells." (PMID 28790362, 2017).
lung carcinoma (continued). "Here, we have demonstrated that the endogenous levels of TLR3 mRNA are variable amongst lung, breast and colon cancer cell lines tested, and there is heterogeneity even amongst different cell lines within the same type of cancer, e.g. lung cancer (A549, NCI-H292, NCI-H358, NCI-H1299)." (PMID 28427199, 2017). "In this study, we demonstrated that FFAR2 was negatively involved in lung cancer progression induced by TLR2 and TLR3 through the suppression of the cAMP-AMPK-TAK1 signaling axis for the activation of NF-κB." (PMID 37287005, 2023). "The engagement of TLR3/4 was reported to induce increases in the production of IL-6, CCL2, CCL20, VEGF, and MMP2 through NF-κB activation, thereby enhancing lung cancer migration and invasion." (PMID 37287005, 2023). "Functionally, treatment with propionate (an agonist of FFAR2) significantly inhibited human lung cancer migration, invasion, and colony formation induced by TLR2 or TLR3 by attenuating the cAMP-AMPK-TAK1 signaling axis for the activation of NF-κB." (PMID 37287005, 2023). "To understand how Hiltonol kills lung cancer cells, we first examined MDA5 and TLR3, which are PRRs (pattern recognition receptors) that bind dsRNAs." (PMID 33562773, 2021). "Estornes and colleagues demonstrated that Poly(I:C) interaction with TLR3 promotes the binding of TRIF and the subsequent recruitment of RIP1 and caspase 8, to finally trigger apoptosis in lung cancer cell lines." (PMID 33147700, 2020). "We incubated HEK-Blue cells expressing human TLR2, TLR3, TLR4, TLR5, TLR7, TLR8, TLR9, or the intracellular PRR protein NOD2 with 100 μg/ml DRibbles derived from the mycoplasma free lung cancer cell line UbiLT3." (PMID 27490927, 2016). "TLR3/4 activation results in the upregulation of chemokines CCL2/MCP-1 and immunosuppressive factors VEGFA and MMP2, which collectively promotes lung cancer invasion and metastasis through the adaptor protein TICAM1/TRIF and the activation of downstream MAPK/NF-κB signaling pathway." (PMID 41293166, 2025). "Importantly, we found that FFAR2KO A549 and FFAR2KO H1299 lung cancer cells exhibited the enhancement of cell migration, invasion, and colony formation induced by TLR2 and TLR3, along with increases in the production of CCL2, IL-6, and MMP2 cytokines." (PMID 37287005, 2023). "Engagements of TLR3/TLR4 can induce the activation of NF-κB through the TRAF6-TAB2 signaling axis (left) and autophagy through the TRAF6-BECN1 signaling axis (right), eventually facilitating lung cancer progression." (PMID 37443143, 2023). "Functionally, treatment with propionate (an agonist of FFAR2) significantly inhibited human A549 or H1299 lung cancer migration, invasion, and colony formation induced by TLR2 or TLR3 through the attenuation of the cAMP-AMPK-TAK1 signaling axis for the activation of NF-κB." (PMID 37287005, 2023). "Previous reports have demonstrated that TLR3/4 activation can increase the production of IL-6, CCL2, MMP2, and CCL20 cytokines by promoting TRAF6 ubiquitination and autophagy induction, thereby facilitating the migration and invasion of lung cancer cells." (PMID 35422093, 2022). "Autophagy induced by TLR4 or TLR3 activation can enhance the production of cytokines such as IL-6, CCL2, MMP2, and CCL20 by promoting TRAF6 ubiquitination, thus facilitating the migration and invasion of lung cancer cells." (PMID 35422093, 2022). "In summary, our data showed that human lung cancer cell-derived MPs, due to their ability to carry unique noncoding RNAs, result in the activation of TLR3 and the subsequent pro-IL-1β production in macrophages." (PMID 31649305, 2020). "Thus, besides these effects of TLR3 activation on immune cells, our data indicate that TLR3 activation on cancer cells by promoting apoptosis may in turn favor the activation of an immune response against the tumor and thus improve the prognosis of lung cancer patients." (PMID 32093313, 2020).
lung carcinoma (continued). "One hundred and thirty-nine lung cancer specimens, including 53 ADC, 47 squamous cell carcinoma (SCC), 30 sarcomatoïd carcinoma (SC), and nine small cell lung carcinoma (SCLC), were analyzed for TLR3 expression by immunohistochemistry." (PMID 30158588, 2018). "Flow cytometry showed TLR3 to be intracellularly expressed in lung cancer cells, unlike the aberrant expression of cell surface TLR3 in HCC." (PMID 28427199, 2017). "Consequently, ARRB2 can inhibit lung cancer progression regulated by two signaling axes, TRAF6-TAB2 signaling axis for NF-κB activation and the TRAF6-BECN1 signaling axis for autophagy induction, in response to TLR3 and TLR4 stimulation." (PMID 37443143, 2023). "Notably, FFAR2KO human lung cancer FFAR2KO A549 and FFAR2KO H1299 cells showed marked increases in cell migration, invasion, and colony formation in response to TLR2 or TLR3 stimulation, accompanied by elevations in NF-κB activation, cAMP levels, and the production of CCL2, IL-6, and MMP2 cytokines." (PMID 37287005, 2023). "Hitherto, information is lacking on the functional effects of polyI:C on TLR3 in lung cancer." (PMID 28427199, 2017). "TLR3 antibody blocked TLR3 signalling without decreasing the viability of the lung cancer cells." (PMID 28427199, 2017). "Our results suggest that FFAR2 signaling antagonized TLR2- and TLR3-induced lung cancer progression via the suppression of the cAMP-AMPK-TAK1 signaling axis for the activation of NF-κB, and its agonist might be a potential therapeutic agent for the treatment of lung cancer." (PMID 37287005, 2023). "Moreover, stimulation with TLR4 and TLR3 can induce the production of IL-6, CCL2/MCP-1, CCL20/MIP-3α, VEGFA (vascular endothelial growth factor A), and MMP2 known to play pivotal roles in the migration and invasion of lung cancer cells through induction of autophagy." (PMID 37443143, 2023). "A549 and H1299 lung cancer cells were treated with vehicle, HKLM (an agonist of TLR2), or poly(I:C) (an agonist of TLR3) in the presence or absence of propionate (an agonist of FFAR2), and the cell migration assay was performed." (PMID 37287005, 2023). "The clinical TCGA data showed a significant down-regulation of FFAR2, but not FFAR1, FFAR3, and FFAR4, in lung cancer, and a negative correlation with TLR2 and TLR3." (PMID 37287005, 2023). "Notably, lung cancer cell lines, A549 (non-metastatic) and NCI-H292 (metastatic), express substantial endogenous levels of TLR3 mRNA when not treated with polyI:C (NT white bars) but they express low levels of TLR3 protein compared to those of NCI-H358 and NCI-H1299." (PMID 28427199, 2017).
herpes simplex encephalitis (41 papers, 2009 to 2025). Herpes simplex virus encephalitis (HSE) is caused by the infection of the central nervous system by Herpes simplex virus (HSV) that could have a devastating clinical course and a potentially fatal outcome particularly with delay or lack of treatment. "TLR3 deficiency due to the p.Pro554Ser variant confers an autosomal dominant predisposition to herpes simplex virus encephalitis and to COVID-19 infection, with incomplete clinical penetrance." (PMID 38976510, 2025). "The most characteristic clinical manifestation of TLR3 deficiency in children is herpes simplex encephalitis (HSE) caused by herpes simplex virus type 1 (HSV-1)." (PMID 41369391, 2025). "TLR3 deficiency has also been shown to increase the risk of other diseases, such as herpes simplex encephalitis and Coxsackie virus infection, supporting the role of the TLR3-mediated immune response." (PMID 38907187, 2024). "For instance, it is well established that defects of the TLR3 signaling pathway increase susceptibility to HSV encephalitis (HSE), and remarkably, POL III mutations were not identified in whole exome sequencing of large cohorts of HSE patients." (PMID 32495195, 2020). "For example, human TLR3 has been implicated in the neuroprotection against herpes simplex virus 1 infection, with loss-of-function mutations in the corresponding gene associated with susceptibility to herpes simplex encephalitis." (PMID 41267809, 2025). "Also, as has been shown for the Toll-like receptor 3 (TLR3) pathway, mutations in genes that are biological interaction partners can lead to the same disease, in this case herpes simplex encephalitis (HSE)." (PMID 29225788, 2017). "For instance, TLR3 deficiency in patients is associated with herpes simplex encephalitis." (PMID 27662626, 2016). "The interrelationship between polymorphisms in TLR3 and susceptibility to herpesvirus disease was demonstrated in studies linking HSV encephalitis to a specific TLR3 polymorphism associated with diminished inflammatory cytokine production following stimulation with an agonist." (PMID 24023565, 2013). "The significance of TLR3 in sensing HSV has been corroborated by studies showing that TLR3 deficiency in humans is associated with increased susceptibility to herpes simplex encephalitis, although this is mainly due to impairment of local responses rather than a defect a CD8 T cell responses." (PMID 24204273, 2013). "Mutations in TLR3 impair TLR3 responses and confer a predisposition to herpes simplex encephalitis." (PMID 21197407, 2010). "Children with germline mutations in components of the TLR-3 pathway are highly susceptible to herpes simplex encephalitis (HSE) due to impaired IFN responses (30, 35, –, 37, 168, 169)." (PMID 40552831, 2025). "TLR3 is implicated in the pathogenesis of many inflammatory diseases, such as the coronavirus disease (COVID-19), herpes simplex encephalitis (HSE) and Paracoccidioides brasiliensis infections." (PMID 38172683, 2024). "Similarly, patients with a TLR3 deficiency are highly susceptible to Herpes Simplex encephalitis." (PMID 19122812, 2009). "For defects affecting antiviral TLR pathways, such as TLR3 and UNC93B1 deficiencies, early recognition and treatment of herpes simplex virus (HSV) infections are crucial to prevent HSV encephalitis." (PMID 41369391, 2025). "Gene mutations in nucleic acid sensing components such as TLR3 or its downstream signaling molecules (including UNC93B1, TLR3, TRIF, TRAF3, TBK1, IRF3, etc.)are one of the causes of herpes simplex encephalitis." (PMID 38814453, 2024). "Previous studies have uncovered defects in the innate Toll-like receptor 3 pathway and production of type I interferon (IFN-I) in children and adults that predispose them to herpes simplex encephalitis." (PMID 36839582, 2023). "Likewise, forebrain herpes simplex encephalitis (HSE) can be caused by IEI of TLR3-dependent type I IFN immunity resulting from mutations of eight genes." (PMID 37196358, 2023).
herpes simplex encephalitis (continued). "The relevance of TLR3 during HSV infection is discussed in more detail below (see “Herpes simplex encephalitis”)." (PMID 34676800, 2021). "Mutations in the IRF3 gene in herpes simplex encephalitis (HSE) patients impaired interferon production and the TLR3-TRIF pathway is the most severely damaged." (PMID 30967139, 2019). "Identified genetic defects in individuals with herpes simplex encephalitis (HSE) and varicella zoster virus encephalitis include mutations in the sensing and signaling pathways for the pattern recognition receptors (PRRs) TLR3 and RNA polymerase III, leading to impaired type I IFN responses." (PMID 37937644, 2023). "Classic examples of this are Mendelian susceptibility to mycobacterial disease (MSMD), which results from impaired IFNγ-mediated immunity following exposure to mycobacterial species, and herpes simplex virus encephalitis (HSE) resulting from impaired TLR3-mediated anti-HSV1 immunity." (PMID 33598806, 2021). "It has been reported that a dominant-negative TLR3 allele is associated with the development of herpes simplex encephalitis, suggesting that TLR3 plays a protective role in herpes simplex virus infection." (PMID 22189096, 2011). "Accordingly, mutations present in genes of the TLR3 signaling pathway, such as the gene encoding for TANK-binding kinase 1 (TBK1), correlated with the development of herpes simplex encephalitis (HSE) in children and young adults." (PMID 31114761, 2019). "Homozygous mutation in IRF7 led to a near-fatal infection by influenza virus, while mutations in TLR3 and in several other T1IFN-related genes markedly increase the risk of herpes simplex encephalitis (HSE)." (PMID 27580079, 2016). "Furthermore, a dominant negative TLR3 allele was found in patients suffering from Herpes Simplex encephalitis implying a role for this receptor in protection from neurotropic viruses." (PMID 19122812, 2009). "Additionally, some fatal cases of herpes simplex encephalitis (HSE) are associated with defects in key genes in the interferon signaling pathway, such as TRIF, TBK-1, TLR3, and TRAF3." (PMID 40285022, 2025). "Variants in TLR3 as well as TRIF, TRAF3, TBK1, IRF3, and NEMO that code for mediators downstream of TLR3, and UNC93B1 that is involved in TLR3 trafficking, all reduce type I interferon signaling and are reported genetic causes of herpes simplex encephalitis (HSE)." (PMID 35126383, 2021). "Patients, especially children with deficiencies in TLR3 or single-gene errors in components of the TLR3 signaling pathway, are more susceptible to HSV-1 and HSV-2 infections, which may be the cause of a devastating human disease—herpes simplex encephalitis (HSE)." (PMID 31089414, 2019).